APRT (adenine phosphoribosyltransferase)
Description:
Catalyzes a salvage reaction resulting in the formation of AMP, that is energically less costly than de novo synthesis.
Synonyms: AMP; APRTD
Tractability: Small molecule: a structure with a bound ligand is known; it has a high-quality binding pocket. Antibody: its Gene Ontology location is reachable by antibodies, with high confidence. PROTAC: ubiquitination databases record sites on it; its protein half-life has been measured; a small molecule that binds it is known.
Target class: Enzyme; Transferase
Gene: Protein-coding gene on chromosome 16 (88,809,339 to 88,811,963, reverse strand). Ensembl gene ENSG00000198931.
Subcellular location: Cytoplasm
Subcellular location (Human Protein Atlas): Cytosol; Nucleoplasm
Pathways (Reactome):
Disease: Defective APRT disrupts adenine salvage
Immune System: Neutrophil degranulation
Metabolism: Purine salvage
Gene Ontology:
Molecular function: adenine phosphoribosyltransferase activity; AMP binding; protein binding; adenine binding; heterocyclic compound binding
Biological process: adenine salvage; AMP salvage; GMP salvage; IMP salvage
Cellular component: cytosol; extracellular exosome; cytoplasm; extracellular region; secretory granule lumen
Genetic constraint (gnomAD): Loss-of-function variants: 25 observed, 19.07 expected, observed/expected ratio (o/e) 1.31, 90% interval 0.95 to 1.79. The synonymous counts are far from expectation, so gnomAD's model fits this gene poorly and the ratio says little. Missense variants: 294 observed, 219.88 expected, observed/expected ratio (o/e) 1.34, 90% interval 1.22 to 1.47. Synonymous variants: 153 observed, 101.21 expected, observed/expected ratio (o/e) 1.51, 90% interval 1.33 to 1.73.
Homologues: Orthologues: chimpanzee APRT (100% identical), guinea pig APRT (87% identical), dog APRT (86% identical), mouse Aprt (83% identical), pig APRT (73% identical), tropical clawed frog aprt (59% identical), zebrafish aprt (53% identical), Drosophila melanogaster Aprt (44% identical), Caenorhabditis elegans aprt-1 (41% identical).